RAC1 (Rac family small GTPase 1)
Diseases named in the same sentence as RAC1 in open-access papers (continued):
Sharing a sentence is not in itself a finding about the gene and the disease.
tumor (continued). "As known, endothelial migration is essential for tumor cell invasion, where ROS/RAC1–NADPH–oxidase complex induces expression of matrix metalloproteinases (MMPs) after growth factor and tumor promoter stimulation." (PMID 36387162, 2022). "The RAC1 functions that control cellular adhesion and motility are critical for tumor cells to undergo a multistep metastasis process." (PMID 35534866, 2022). "Collectively, we showed that dysregulated miR-371b-5p/CSDE1/RAC1 axis deepens tumor progression and aggressiveness in patients with TNBC and suggested that miR-371b-5p is a potential prognostic biomarker for TNBC." (PMID 35490208, 2022). "Rac1 not only participates in the formation, progression, invasiveness, and angiogenesis of tumors, but also mediates tumor cell resistance to radiotherapy, chemotherapy, and immunotherapy." (PMID 35031595, 2022). "It has been found that the dysregulated expression of GEFs, which are responsible for Rac1 activation, is closely related to tumor metastasis and drug resistance." (PMID 35682879, 2022). "For example, Naa10p interacts with PIX proteins to inhibit Cdc42/Rac1 activity and thus suppress cell motility and tumor metastasis." (PMID 36433943, 2022). "We found that the expression level of Rac1 in tumor tissues was significantly higher in BRCA, KICH, KIRP, and THCA, and we should also pay attention to the role of Rac1 in KICH, KIRP, and THCA." (PMID 36059952, 2022). "In summary, we identified MG53 as a novel RAC1 inhibitor and tumor suppressor in HCC, and it suppressed HCC progression by inducing K48-linked polyubiquitination of RAC1 and further inhibiting the RAC1-MAPK signaling." (PMID 35858925, 2022). "Regarding Rac1’s particular roles for tumor metastasis, the therapeutic potentials of super high ligand density are promising." (PMID 36008449, 2022). "Rac Family Small GTPase 1 (RAC1) is a regulator of several cell processes, such as cell cycle, intercellular adhesion, movement, and epithelial differentiation, and functions as a tumor oncogene in HCC." (PMID 36345477, 2022). "There is abundant evidence for the central role of the Rho GTPase Rac1 for tumour invasiveness and metastatic growth." (PMID 36377725, 2022). "Because of the role of Rac1 in tumor progression, our findings provide a theoretical basis for the development of drugs targeting CBX3 to treat LUAD." (PMID 34785774, 2022). "It was found that the high expression of Rac1 protein was closely related to the differentiation, staging and lymph node metastasis of tumor." (PMID 34079763, 2021). "A recent E3 ligase identified as regulating the ubiquitylation of Rac1 and Rac2 in human tumor cells is the HECT domain and ankyrin repeat containing E3 ubiquitin protein ligase 1 (HACE1)." (PMID 34440759, 2021). "Studies have demonstrated that superoxide production by RAC1-dependent NADPH oxidase is critical for WNT signaling and necessary for tumor formation after APC loss." (PMID 33557356, 2021). "Presence of S1PR1 leads to VEGFR2 phosphorylation at Y951, which retains VEGFR2 at the EC surface and promotes migration and tumor growth via sustained Rac1 activity." (PMID 34690821, 2021). "Some molecules have been highlighted as pro-angiogenic factors during tumour progression, such as RAC1, MMPs, TIMP, and NCK1." (PMID 34827551, 2021). "The malignant transformation of tumor is mainly related to over-activation or over-expression of Rac1." (PMID 34079763, 2021). "Another study showed that silencing Rac1 expression in the whole tumour xenograft, reduced tumour growth and angiogenesis and inhibited VEGF-induced neovascularisation of Matrigel plugs in vivo." (PMID 33573141, 2021). "The impact and relevance of Rac1 in tumor progression is consistent with the breadth of its various activating mechanisms and the variety of tumor types affected." (PMID 33914026, 2021).
tumor (continued). "Mice harboring bigenic tumors contained a greater number of circulating tumor cells and lung metastases as well as higher levels of activated Smad2, Akt, Erk, p38, Rac1 and more vimentin in the tumor tissues in situ than tumors expressing Neu alone." (PMID 33478130, 2021). "Grouping 365 tumor samples with high and low expression of RAC1, we found differences in the infiltration of nine immune cells in the TCGA cohort." (PMID 35493265, 2021). "RAC1B is a tumour-related alternative splice isoform of the small GTPase RAC1, found overexpressed in a large number of tumour types." (PMID 34564693, 2021). "The tumour suppressor RRM2 was slightly upregulated in 48 h treatment whereas Rac1, a protein contributing to invasion, was less abundant in NBL cells treated with MEVs for 72 h." (PMID 33805332, 2021). "Instead, rAC1 with a moderate affinity (KD of 4 nM) demonstrated a faster rate of tumor accumulation than the other high-affinity binders, rEgA and rEgH9." (PMID 33615202, 2021). "HACE1 is described as a tumor suppressor that catalyzes the degradative ubiquitination of active Rac1 (Ras-related C3 botulinum toxin substrate 1) GTPase." (PMID 33800394, 2021). "The role of RAC1 in ovarian cancer has briefly been explored, showing interactions with signalling events that mediate tumour metastasis." (PMID 34830751, 2021). "When subjected to DMBA/TPA treatment, the Vav2−/−Vav3−/− double knockout animals develop tumors with a slower kinetic than control mice, and much like the Rac1-epidermal null animals, their tumor burden is reduced." (PMID 34503171, 2021). "Given that RAC1 activity is vital to tumour development and progression, there is much focus on RAC1 as a pharmacological target." (PMID 33397922, 2021). "The high expression level of the Rac1 protein was closely related to the tumor site of the RMS patients (P = 0.025)." (PMID 34221974, 2021). "Studies have shown that the activation and expression of Rac1 affect the survival prognosis of many tumor diseases." (PMID 34221974, 2021). "This is due to the formation of a special drug resistance mechanism in tumors, and Rac1 plays an important role in regulating drug resistance in tumor treatment." (PMID 34079763, 2021). "CDKN2B-AS1 targeted miR-141 to induce tumor progression and metastasis in renal cell carcinoma via the cyclin D/RAC1/paxillin network." (PMID 34771549, 2021). "For example, a recent study has revealed that abnormal Rac1 activity and expression were closely related to tumor characteristics such as tumor genesis, survival, metastasis, anti-apoptosis, and drug resistance." (PMID 35265666, 2021). "In tumor tissues, the active form of RAC1 is involved in regulating the movement of tumor cells and affecting tumor growth by regulating the filopodia and membrane shrinkage." (PMID 35493265, 2021). "Taken together, these findings indicate an intricate involvement of Rac1 in tumour development, driven by EC-specific expression." (PMID 33573141, 2021). "Rac1, as a cytoskeletal regulator, regulates the polymerization of actin and promotes the migration and invasion of tumor cells, thus playing a key role in tumor evolution." (PMID 34079763, 2021). "Studies have shown that Rac1 not only participates in the tumor cell cycle, apoptosis, proliferation, invasion, migration and angiogenesis, but also participates in the regulation of tumor stem cell, thus promoting the occurrence of tumors." (PMID 34079763, 2021). "Rac1 also plays a key role in anti-tumor therapy and participates in immune escape mediated by the tumor microenvironment." (PMID 34079763, 2021). "Oral administration of R-ketorolac for 2 weeks significantly decreased the activity of Rac1 and Cdc42 in tumor lysates when compared to those from placebo control groups." (PMID 33413202, 2021). "1D-142 targeted inhibition of RAC1 can produce a powerful anti-tumor effect in highly proliferative HCC." (PMID 35493265, 2021).
tumor (continued). "As an inhibitor of Rac1, its most essential role is to inhibit the tumorigenicity mediated by Rac1 and the malignant biological behaviors of different tumor cells, such as cell migration, cell invasion, and rearrangement of actin skeleton." (PMID 34079763, 2021). "RAC1 GTPase was also found to signal Wnt-beta-catenin pathway-mediated tumor cell phenotypes which are involved in proliferation, tumorigenesis, and metastatic events." (PMID 34229299, 2021). "R-ketorolac treatment inhibited tumor Rac1 and Cdc42 activity with little impact on mRNA or protein expression of these GTPase targets." (PMID 33413202, 2021). "Specifically, HGF/Met induces the proliferation and migration of endothelial and tumour cells through RhoA, Rac1, and Cdc42 activation." (PMID 34202487, 2021). "RAC1 activation has also been shown to regulate the mode of cell movement to promote colonization of tumor cells." (PMID 34827551, 2021). "In mice, studies have shown that the specific deletion of Rac1 in keratinocytes is sufficient to reduce the tumor burden of animals treated with DMBA/TPA when compared to treated controls." (PMID 34503171, 2021). "Overexpression of Rac1 enhances cell proliferation and migration, and plays an important role in the invasion and migration of many tumor cells." (PMID 34079763, 2021). "We next quantified the average copy number of the RAC1 gene in the patient tumor samples before treatment and at progression." (PMID 34638434, 2021). "Treatment with R-ketorolac at dosing comparable to that achieved in patients receiving racemic (R−/S-) ketorolac inhibited tumor Rac1 and Cdc42 activity and decreased tumor burden." (PMID 33413202, 2021). "We find that R-ketorolac, a dual Rac1/Cdc42 inhibitor, decreased tumor burden in both a short-term omental engraftment assay and a two-week tumor growth study." (PMID 33413202, 2021). "RAC1 can induce plasma membrane protrusions to form a lamellar layered pseudopod, regulate tumor cell adhesion, and contribute to cell invasion and metastasis." (PMID 32419796, 2020). "Like other members of the Rho-family of GTPase, RAC1 has a limited transcriptional role in a tumor cell." (PMID 32545340, 2020). "Rac1 is over activated in a wide range of tumor types and and it is one of the most studied proteins of the Rho GTPase family." (PMID 32351958, 2020). "RH derivative 4F as a novel anthraquinone compound with better anti-tumor activity through the more stably binding to Rac1 and inhibiting Rac1 promoter activity in cells and down-regulating Rac1 protein expression." (PMID 33101021, 2020). "IHC staining of the tumor sections confirmed the decreased level of Rac1 and p-ERK in shRac1 tumors." (PMID 32193458, 2020). "Rac1 and RhoA regulation of focal complexes assembly and maturation into focal adhesions is required for the effective cell migration of different tumor models." (PMID 32900380, 2020). "Their study outcomes further revealed that miR-124 targets the 3′-untranslated region of Rac1 (supposed tumor promoter in PDAC) directly." (PMID 33490232, 2020). "These phenotypes are by no means mutually exclusive and are merely an attempt to organize the existing literature regarding RAC1 in tumor progression and therapeutic resistance." (PMID 32545340, 2020). "On the other hand, tumor increased at a lower rate in nude mice in the sh-RAC1 compared with sh-control group, and tumor weight was smaller in the sh-RAC1 group." (PMID 32411607, 2020). "The events triggered by Ras oncogenes and facilitated by Rac1 and its effectors point at the therapeutic potential of targeting Ca2+/calmodulin in tumour growth and metastasis." (PMID 32456244, 2020). "Firstly, disruption of Ras/PI3K interaction leads to inhibition of Rac1 activation and tumour regression in a mouse model for EGFR mutant lung adenocarcinoma." (PMID 32456244, 2020).
tumor (continued). "Activated cAbl1 induces phosphorylation of VEGFR2 at Y951, promoting receptor retention at the EC surface which in a sustained manner induces Rac1 activity and EC migration and tumor angiogenesis." (PMID 32944615, 2020). "A previous study showed that PODXL-promoted tumor metastasis was mediated by activating the Ras-related C3 botulinum toxin substrate 1 (Rac1) signaling cascade or PI3K/Akt signaling." (PMID 32669966, 2020). "These functions of RhoA and Rac1 become crucial for angiogenesis and tumour initiation, invasion and metastasis." (PMID 32731493, 2020). "Cell-surface retained VEGFR2 persistently activated Rac1 following VEGF addition which in turn promoted EC migration to tumor for vascularization and growth." (PMID 32944615, 2020). "RhoA, Rac1 and Ras are members of Ras super family of small GTPases that are critically involved in tumor cell biological activities such as migration, growth and survival." (PMID 32085741, 2020). "Consistent with the in vitro results, RAC1 significantly enhanced tumor xenograft growth treated with IR." (PMID 32411607, 2020). "Calmodulin-dependent GTPase signalling is coupled to pathological settings, as KRas and Rac1 are often drivers of signalling pathways that critically stimulate tumour formation and progression." (PMID 32456244, 2020). "This was consistent with the antagonistic relationship between RhoA and Rac1 observed in other tumor types." (PMID 32900380, 2020). "By constitutively expressing an activated form of Rac1 (Rac1V12) along with oncogenic Ras through adulthood, Lucy Dalton and her colleagues showed an essential role for Rac1 in accelerating tumor nodule formation in a zebrafish model of melanocyte neoplasia." (PMID 33302361, 2020). "Our previous tumor biological experiments also showed that Rhein plays an anti-tumor role by combining Rac1." (PMID 32547389, 2020). "Nevertheless, Rac1 protein proved to be overexpressed in CRC and significantly associated with tumor stage." (PMID 32178475, 2020). "Rac1 is reported to play both tumor-promoting role and tumor-suppression role in certain kinds of tumors, which indicates that the function of Rac1 remains controversial and is related to a complex network of tumor regulation." (PMID 33604328, 2020). "Numerous studies have shown that Rac1 is intricately linked with Hippo, ERK, and PAK signaling pathways in tumor progression 27-34." (PMID 33042270, 2020). "Domain-mutated Porf-2 plasmids were then constructed, and it was found that the GAP domain, which plays a role in the inactivation of Rac1, is the functional domain for inhibiting tumor cell migration." (PMID 32676454, 2020). "For instance, nuclear RAC1 has been shown to promote cell division and its nucleocytoplasmic shuttling drives nuclear shape changes and tumor invasion." (PMID 33266416, 2020). "In contrast, sh-RAC1 group showed a decreased size of tumors responding to IR, but sh-RAC1 significantly inhibited the tumor xenograft growth treated with IR." (PMID 32411607, 2020). "Rac1 knockdown slightly deceased the tumor growth, while cisplatin treatment moderately decreased the tumor growth in vivo." (PMID 32193458, 2020). "Tumor increased at a much rapid rate in nude mice in the RAC1 compared with the control group (P < 0.05), while tumor weight was significantly larger in the RAC1 group." (PMID 32411607, 2020). "The expressions of RAC1, Ki-67, and activated caspase-3 were detected in the xenograft tumor tissues of A549 cells in mice." (PMID 32411607, 2020). "For example, EHop-016 blocks the interaction of Rac1 with Vav2, and has been shown to enhance the anti-tumor effect of cisplatin in xenograft models of esophageal squamous cell carcinoma." (PMID 32309283, 2020). "When we performed a pulldown assay of RAC1 in extracts from vehicle and GA-treated tumours, there was less active RAC1 in the tumours treated with GA." (PMID 31578236, 2019).
tumor (continued). "RAC1 overexpression can activate the PAK or ERK pathway to enhance tumour growth and aggressiveness." (PMID 31873123, 2019). "We have reviewed the activation and regulation of RAC1 functions on the basis of its sub-cellular localization in tumor cells." (PMID 31027363, 2019). "Rac1 and Cdc42 are regulators of numerous functions related to tumor development, progression, metastasis, and chemo-resistance." (PMID 31344967, 2019). "This highlights the important contribution of dysregulated endocytic signaling to cell transformation and suggests that endosomal Rac1 signaling contributes to tumor progression triggered by oncogenic c-Met mutants." (PMID 31766364, 2019). "The major target site for Rac1 ubiquitination is Lys147 and seems to be dependent on JNK (Jun N-terminal Kinase) activation, although also the tumor suppressor HACE1 has a role in the regulation of Rac1 ubiquitylation and activity." (PMID 31035701, 2019). "The role of Rac1 in tumor progression is well established; Rac1 is overexpressed in different types of tumors and is important for malignant transformation." (PMID 31514269, 2019). "RAC1 has been reported to play important roles in cell movement, tumor angiogenesis and invasion/metastasis." (PMID 31068775, 2019). "HACE1 is considered as a tumor suppressor for degradation of Rac1 since HACE1 inhibits reactive oxygen species (ROS) generation by Rac1-dependent NADPH oxidases." (PMID 31248165, 2019). "Nucleocytoplasmic shuttling of RAC1 has been reported to drive nuclear shape changes and tumor invasion." (PMID 31027363, 2019). "It was reported to suppress tumor invasiveness and angiogenesis through blockage of Rac1 and its downstream mediators, which include F-actin polymerization and vascular endothelial growth factor (VEGF)." (PMID 31817720, 2019). "This was paralleled by a 44% decrease of Rac1 expression in tumor tissue compared to siRac1-alone-treated mice." (PMID 31652539, 2019). "Our results indicate that high RAC1 levels in tumor correlate with poor prognosis in ESCC patients, and it is confirmed by our in vitro data, which demonstrate that RAC1 positively regulates proliferation and migration of ESCC cells." (PMID 31314174, 2019). "We evaluated RAC1 expression in 106 tumor samples of ESCC patients using IHC and anti‐RAC1 monoclonal antibody." (PMID 31314174, 2019). "First, as an integrator of upstream signals generated by receptor tyrosine kinases, G-protein-coupled receptors, integrins, and other adhesion molecules, Rac1 activity varies based on factors within the tumor microenvironment." (PMID 31344967, 2019). "Rac1 is well known as a tumor progression factor because it participates in cell migration/invasion and proliferation." (PMID 30696065, 2019). "Next, we performed MTS, EdU, wound healing, and Transwell assays to explore the role of RAC1 in tumor proliferation and migration." (PMID 31314174, 2019). "Once activated, Rab5 recruits a number of interacting proteins, such as Rac1 and Tiam1, which play an important role in tumor metastasis." (PMID 31338333, 2019). "Control of Rac1 nuclear accumulation by NPM leads to 2 functional consequences, altering the nuclear membrane organization and regulating the cytoplasmic ratio of Rac1 and Rho, thus modulating cell migration and tumor invasion." (PMID 31195150, 2019). "Rac1 and Cdc42 are the key members of Rho GTPases, and they can modulate the formation of membrane protrusions during tumor cell migration." (PMID 31057403, 2019). "Increasing evidence over the past few years indicates that Rac3 plays an important role in neuronal development and in tumor progression, with specificities that distinguish the functions of Rac3 from the established functions of Rac1 in these processes." (PMID 31514269, 2019).